PTH (parathyroid hormone)
Diseases named in the same sentence as PTH in open-access papers (continued):
Sharing a sentence is not in itself a finding about the gene and the disease.
Hypercalcemia (continued). "Primary hyperparathyroidism (PHPT) results from inappropriate overproduction of parathyroid hormone from one or many parathyroid gland(s) and presents with hypercalcemia." (PMID 21747852, 2011). "All studies confirm that cinacalcet effectively controls hypercalcemia while only modestly reducing PTH levels in pHPT." (PMID 21461394, 2011). "Patients with FHH are heterozygous for the CaR mutation and have a normal or mildly increased circulating parathyroid hormone (PTH) level, normal parathyroid histology or mild parathyroid hyperplasia, and mild to moderate hypercalcemia." (PMID 21966280, 2011). "Primary hyperparathyroidism (PHPT) is a common endocrine disorder, usually sporadic and asymptomatic, characterized by inappropriate hypersecretion of parathyroid hormone (PTH) and hypercalcemia." (PMID 22185226, 2011). "Postoperatively, the patient had normalization of hypercalcemia and parathyroid hormone levels, with subsequent healing of her thigh wounds." (PMID 20885925, 2010). "Serum PTH and 1-25(OH)2D3 were low in most cases due to suppression of the parathyroid glands and renal α-hydroxylase secondary to hypercalcemia." (PMID 20959010, 2010). "This 80-year-old woman was noted to have hypercalcemia, relative hypocalciuria, and an elevated PTH level." (PMID 21034470, 2010). "We suggest that all first-degree relatives of patients with hypercalcemia and inappropriately normal or elevated PTH levels should have a calcium level determined." (PMID 21034470, 2010). "Laboratory workup frequently shows hypercalcemia, hyperphosphatemia, and increased parathyroid hormone levels." (PMID 19646226, 2009). "Presentation of hypercalcemia and normal PTH level due to parathyroid adenoma is infrequent; however, its incidence has been estimated to be between 5% and 33%." (PMID 18291038, 2008). "Several small studies have reported that calcimimetics reduced PTH levels and hypercalcaemia after renal transplantation." (PMID 18594867, 2008). "The mechanism of hypercalcemia is PTH-independent extrarenal production of calcitriol from calcidiol by activated mononuclear cells within the granuloma." (PMID 18687121, 2008). "Hypercalcemia in patients with thymoma can be seen due to the following reasons, namely, secretion of parathyroid-related protein (PTHrP) or PTH by the thymoma itself, coexistence of parathyroid adenoma or hyperplasia of parathyroid gland." (PMID 18652699, 2008). "We present a case of persistent hypercalcemia with a normal level of intact-PTH due to a substernal oxyphil parathyroid adenoma positive for PTHrP, treated by radioguided parathyroidectomy." (PMID 18291038, 2008). "We present a case of persistent hypercalcemia with a normal level of intact-parathyroid hormone due to a substernal parathyroid adenoma, treated with radioguided parathyroidectomy." (PMID 18291038, 2008). "PTH level is the classic discriminator between parathyroid disease-dependent hypercalcemia and others, whereas PTHrP is the most useful analytical method in HHM." (PMID 18291038, 2008). "Laboratory tests on admission showed hypercalcemia (12.7 mg/dL), hypophosphatemia (0.90 mg/dL), normal intact-PTH level (41.0 pg/mL) and an increase in 1,25-dihydroxycholecalciferol level (148.7 pg/mL)." (PMID 18291038, 2008). "Probably as a result of high serum 1,25(OH)2D3 and concomitant hypercalcemia, serum PTH was undetectable in all three mutant lines." (PMID 18688277, 2008). "Primary hyperparathyroidism (HPT) is characterized by excessive secretion of parathyroid hormone (PTH), and is a leading cause of hypercalcaemia and hypophosphataemia." (PMID 17937802, 2007). "Single parathyroid adenomas, which cause approximately 85% of the cases of primary hyperparathyroidism are well-differentiated, benign, clonal tumors, which produce hypercalcemia through excessive secretion of parathyroid hormone (PTH)." (PMID 17916247, 2007).
Hypercalcemia (continued). "After the stage 1 osteotomy, severe hypercalcemia (peak: 3.79 mmol/L; reference: 2.11-2.52 mmol/L) and elevated PTH (995 pg/mL; reference: 15-65 pg/mL) emerged, leading to Single-photon emission computed tomography (SPECT) confirmed diagnosis of a left inferior parathyroid adenoma." (PMID 41767373, 2026). "Since PCs are mostly functioning, patients typically present with more symptomatic hypercalcemia compared to those with parathyroid adenomas, with serum calcium levels often exceeding 14 mg/dL and serum PTH concentrations usually 5–10 times the upper limit of normal." (PMID 41568161, 2026). "All hypercalcemic patients underwent measurement of serum calcitriol (1,25-dihydroxyvitamin D), PTH, and 25-hydroxyvitamin D (25(OH)D) as per standard hypercalcemia evaluation protocol, with direct calcitriol measurement enabling confirmation of the granulomatous mechanism." (PMID 41658645, 2026). "This case highlights the importance of considering sarcoidosis in PTH-independent hypercalcaemia." (PMID 42281697, 2026). "We report a 63-year-old male with persistent hypercalcemia and inappropriately normal PTH levels." (PMID 42291983, 2026). "Laboratory evaluation showed severe hypercalcemia with suppressed PTH." (PMID 41756472, 2026). "This, in turn, supported the differential diagnosis of non-PTH-mediated hypercalcemia." (PMID 39906031, 2025). "In this condition, which is termed THPT, reduced negative feedback of calcium on PTH secretion, often due to a decreased expression of CaSR in the parathyroid glands, leads to further PTH secretion and calcium elevation, sometimes up to the point of overt hypercalcemia." (PMID 40177730, 2025). "PTH-dependent hypercalcemia, characterized by normal or elevated PTH levels, includes conditions such as primary and tertiary hyperparathyroidism, lithium-induced hypercalcemia, multiple endocrine neoplasia (MEN) disorders, and familial hypocalciuric hypercalcemia." (PMID 40284609, 2025). "Hypercalcemia, alterations in phosphorus metabolism, and other effects of PTH may contribute to the activation of the inflammatory response." (PMID 40731865, 2025). "Normal PTH levels do not exclude primary or secondary hyperparathyroidism as the cause of hypercalcaemia." (PMID 40503605, 2025). "Hence, the authors investigated serum intact PTH levels in gallbladder patients to dichotomise PTH-dependent hypercalcaemia and PTH-independent mechanisms." (PMID 40142228, 2025). "Active forms are more potent but carry higher risks of hypercalcemia and oversuppression of PTH, which may contribute to adynamic bone disease and adverse cardiovascular effects." (PMID 41155582, 2025). "In the case described in this report, the dog's hypercalcemia was presumed to be mediated by vitamin D due to the combination of hyperphosphatemia, suppressed parathyroid hormone, suppressed 25‐hydroxyvitamin D level, and a calcitriol level at the high end of the reference interval." (PMID 41356631, 2025). "However, most PTHrP analogs share a functional similarity to PTH and result in increased serum calcium levels, leading to the potential for hypercalcemia." (PMID 40862730, 2025). "Her brother had mild hypercalcemia (10.8 mg/dL) with a suppressed PTH." (PMID 40765620, 2025). "Primary hyperparathyroidism is a common endocrine disorder defined by abnormally elevated levels of parathyroid hormone (PTH), typically associated with hypercalcemia, or, in some cases, normocalcemia with no identifiable cause for elevated PTH levels." (PMID 41480476, 2025). "Subsequent tests highlighted hypercalcemia and hypophosphatemia with high PTH levels." (PMID 40568365, 2025). "A rise in PTH produces hypercalcemia (increased blood calcium concentration), while a decrease in PTH results in hypocalcemia (lowered blood calcium concentration) that may lead to muscle spasms (tetany)." (PMID 39582410, 2025).
Hypercalcemia (continued). "Interestingly, the patient’s hypercalcemia was non-PTH related, and therefore our differential diagnosis included underlying infectious diseases, malignancies, lymphomas, and granulomatous diseases." (PMID 40520830, 2025). "Elevated PTH and blood calcium levels were first identified in May 2021 at the Endocrinology Research Centre: PTH level – 21.5 pmol/L (up to 6.9 pmol/L), hypercalcemia – 3.2 mmol/L (2.1-2.55 mmol/L), and normophosphatemia – 0.8 mmol/L (0.74-1.52 mmol/L)." (PMID 41323978, 2025). "Persistently elevated PTH and hypercalcemia despite optimal medical management may suggest the transition to THPT, thereby guiding consideration for surgical intervention." (PMID 41301699, 2025). "Increased parathyroid hormone levels production results in hypercalcemia." (PMID 41036144, 2025). "The innate propensity of PTH to activate sustained signaling from endosomes compared to the short-lived signals from the plasma membrane by PTHrP, have been manipulated to design long-acting PTH, which triggers substantially longer cAMP responses and prolonged hypercalcemia." (PMID 39743506, 2025). "Sarcoid granulomas can cause parathyroid hormone (PTH)-independent hypercalcaemia through enhanced conversion of 25-hydroxyvitamin D to 1,25-dihydroxyvitamin D. The incidence of hypercalcaemia as the presenting symptom in sarcoidosis is around 3%; hypercalcaemia is reported in around 10% of cases." (PMID 40381954, 2025). "Primary hyperparathyroidism (PHPT) is a multisystemic endocrine disorder traditionally defined by hypercalcemia and inappropriately elevated parathyroid hormone (PTH) levels; however, a subset of patients displays normal calcium levels, being classified as normocalcemic PHPT." (PMID 40529359, 2025). "Previous studies have suggested that PC could be suspected in patients with severe hypercalcemia (>14 mg/dL), a big size of the tumor and/or with marked elevated PTH levels (>5 times the upper normal limit)." (PMID 40142758, 2025). "Hypercalcemia with a reduced PTH level is suggestive of PTH-independent hyperparathyroidism." (PMID 41479802, 2025). "Hypercalcemia can be classified as PTH-dependent or PTH-independent." (PMID 39851484, 2025). "In light of her persistently suppressed PTH and the non-endocrine mechanism underlying her hypercalcemia, both calcium supplements and calcitriol remained discontinued." (PMID 41018442, 2025). "The differential diagnosis for non-PTH-dependent hypercalcaemia is broad." (PMID 39903584, 2025). "The suppressed endogenous PTH in the setting of persistent hypercalcemia suggested a non-parathyroid cause, with ectopic PTH or PTHrP secretion considered." (PMID 41487858, 2025). "Previous studies have demonstrated that BMD-1141 does not cause hypercalcemia, as observed with daily PTH treatments, except at supratherapeutic doses." (PMID 40862730, 2025). "This is manifested as low/undetectable PTH levels in PTHrP-mediated hypercalcemia." (PMID 41561737, 2025). "Consequently, this can result in hypercalcemia or hyperphosphatemia, which in turn suppresses initial parathyroid hormone (iPTH) level." (PMID 40768409, 2025). "Dorflinger (2019) reports a case in which a patient on long-term lithium therapy experienced hypercalcaemia with a normal serum PTH and no other identifiable cause." (PMID 41185877, 2025). "Laboratory studies revealed hypercalcemia of unknown origin, accompanied by decreased parathyroid hormone (PTH) and elevated PTH-related peptide (PTHrP), raising suspicion for hypercalcemia of malignancy." (PMID 41235016, 2025). "If persistent hypercalcemia is diagnosed during follow-up, further diagnostic evaluation is warranted, including PTH measurement to rule out lithium-induced hyperparathyroidism." (PMID 40182382, 2025).
Hypercalcemia (continued). "A previous report described an IgG4-RD patient with severe hypercalcemia and normal PTH who died on day 16 of hospitalization; autopsy revealed increased osteoclasts and metastatic calcification, though an undetected malignancy could not be excluded." (PMID 41451224, 2025). "However, recurrence of hypercalcemia with suppressed PTH was incompatible with the original diagnosis and required further investigation." (PMID 41009532, 2025). "Indeed, the diagnosis is often established in asymptomatic patients that present few signs of disease other than hypercalcemia and elevated PTH levels." (PMID 39582410, 2025). "The evaluation of hypercalcemia starts by measuring parathyroid hormone (PTH) levels in blood." (PMID 40284609, 2025). "Indications for surgical intervention include persistently elevated PTH levels (>800–1000 pg/mL), with hypercalcemia and/or hyperphosphatemia, despite optimal medical therapy, as well as calciphylaxis, pruritus, severe bone pain/fractures, and/or progressive extraskeletal calcification." (PMID 41227247, 2025). "On the other hand, PTH-induced hypercalcemia might be a contributor to the glucose status disturbances under certain circumstances, including the co-presence of obesity or other non-diabetes metabolic anomalies." (PMID 40283231, 2025). "Given the history of excessive daily milk intake (six pints), calcium supplementation, and vitamin D replacement, combined with hypercalcemia, acute kidney injury, metabolic alkalosis, and suppressed parathyroid hormone (PTH), MAS was diagnosed after excluding other causes of hypercalcemia." (PMID 41141160, 2025). "However, abrupt discontinuation of denosumab can result in a rebound increase in bone turnover, leading to severe, non-PTH-dependent hypercalcemia, as observed in this patient." (PMID 41018442, 2025). "A 43-yr-old woman was seen for non-PTH mediated hypercalcemia." (PMID 40765620, 2025). "The flat exposure profile could translate into lower fluctuations in serum calcium and fewer symptoms due to hypercalcemia and hypocalcemia, compared with PTH agonists with a shorter half-life." (PMID 39574220, 2025). "The diagnosis of PHPT is established in the presence of hypercalcemia and elevated PTH levels." (PMID 40539180, 2025). "Moreover, PTH‐rP, which is responsible for hypercalcemia in approximately 50% of cancer cases, was infrequently measured." (PMID 40067281, 2025). "Laboratory tests revealed severe hypercalcemia and markedly elevated parathyroid hormone levels." (PMID 41293386, 2025). "Two years later, recurrent hypercalcemia occurred with reduced parathyroid hormone levels." (PMID 41479802, 2025). "Excess of vitamin D leads to hypercalcaemia with a suppressed parathyroid hormone." (PMID 41362524, 2025). "PTH plays a central role in calcium homeostasis by promoting hypercalcemia." (PMID 40529990, 2025). "Therefore, hypercalcaemia as a complication of lithium therapy with a normal serum PTH remains an especially underreported phenomenon." (PMID 41185877, 2025). "Patients who underwent thyroidectomy with concomitant parathyroid reimplantation exhibited normocalcemia or mild hypercalcemia (median ≈ 4.7 mg/dL) accompanied by significantly higher PTH levels (≈157 pg/mL), reflecting a transient compensatory response following gland manipulation." (PMID 41373711, 2025). "We hypothesize that the time for resolution of postoperative PTH suppression may vary depending on patient’s level of hypercalcemia, set point level of normal glands, and whether postoperative Ca levels fall below this set point level." (PMID 40810066, 2025). "All the boys had hypercalcemia, hypophosphatemia, hypercalciuria, and elevated PTH levels." (PMID 40666157, 2025).
Hypercalcemia (continued). "Nevertheless, a subset of patients experience either persistent hyperparathyroidism, defined as the failure to normalize calcium and parathyroid hormone (PTH) within six months of surgery, or recurrent hyperparathyroidism, defined as the return of hypercalcemia after a period of normocalcemia." (PMID 41030731, 2025). "Laboratory results showed hypercalcemia with suppression of parathyroid hormone levels." (PMID 39758152, 2025). "Based on all these findings (MRI characters, hypercalcemia with PTH suppression, and hepatosplenomegaly), there were broad differential diagnoses such as multiple myeloma, metastasis, infections (such as tuberculosis), amyloidosis, and metabolic infiltration disorders." (PMID 39758152, 2025). "Primary hyperparathyroidism (PHPT) is a disorder in which calcium metabolism is affected by excessive secretion of parathyroid hormone (PTH) by the parathyroid glands and is the most common cause of hypercalcaemia, which is mainly caused by a single parathyroid adenoma (85%)." (PMID 40161883, 2025). "Notably, patients with primary pancreatic, thymic, or pulmonary NETs manifested as hypercalcemia and elevated PTH require timely evaluation for primary hyperparathyroidism (PHPT)." (PMID 41561737, 2025). "Other etiologies of acute PTH-independent hypercalcemia were investigated by measuring serum angiotensin-converting enzyme (ACE) activity as a nonspecific marker for granulomatous-inflammatory diseases, and PTH-related peptide (PTHrP) for ruling out hypercalcemia of malignancy." (PMID 39906901, 2025). "It is characterized by hypercalcemia and increased or abnormal Parathyroid Hormone (PTH) values." (PMID 40409015, 2025). "Laboratory investigations revealed significant hypercalcemia (ionized calcium 1.69 mmol/L, total calcium unadjusted for albumin 3.44 mmol/L, 13.8 mg/dl), suppressed PTH (<1 pmol/L) and 1,25-dihydroxyvitamin D (<12 pmol/L) and PTH-related peptide was not high (0.9 pmol/L)." (PMID 40547129, 2025). "Additionally, hypercalcemia, normophosphatemia, elevated parathyroid hormone level, and decreased urine calcium excretion were found." (PMID 40357201, 2025). "For this case, the patient developed severe hypercalcemia following denosumab cessation, with laboratory findings of suppressed PTH, normal PTHrP, and normal vitamin D, effectively ruling out primary hyperparathyroidism, humoral hypercalcemia, and vitamin D toxicity as primary etiologies." (PMID 41018442, 2025). "Vitamin D levels, which could exacerbate hypercalcemia through feedback mechanisms with PTH, were assessed in only 43.1% of cases." (PMID 40067281, 2025). "On follow-up, persistent hypercalcemia was documented, with elevated serum PTH levels." (PMID 40182382, 2025). "Moreover, the influence of this variable on osteoporosis outweighs factors closely related to PHPT, such as duration of hypercalcemia, i-PTH levels, and calcium excretion." (PMID 41156271, 2025). "Primary hyperparathyroidism (PHPT) results from a dysregulated increase in PTH secretion by the parathyroid glands, leading to concurrent hypercalcemia, as the parathyroid cells exhibit diminished sensitivity to or insensitivity to the suppressive influence of hypercalcemia." (PMID 39941666, 2025). "The further laboratory blood tests revealed increased PTH level – 141.4 pg/mL (15–65 pg/mL), hypercalcemia with a calcium adjusted for albumin – 2.6 mmol/L (2.15-2.55 mmol/L), normophosphatemia – 0.85 mmol/L (0.74-1.52 mmol/L) daily normocalciuria – 2.9 mmol/day." (PMID 41323978, 2025). "Hypersecretion of PTH drives hypercalcemia and secondary metabolic disturbances." (PMID 40851725, 2025). "This case highlights an atypical presentation of PTH-mediated hypercalcemia." (PMID 39427404, 2024). "When refractory hypercalcemia is present, serum PTH levels should be measured to determine PHPT." (PMID 39020280, 2024). "Post-surgical persistent hypercalcemia and elevated parathyroid hormone (PTH) levels." (PMID 39061231, 2024).